CDKAL1 (CDKAL1 threonylcarbamoyladenosine tRNA methylthiotransferase)
Description:
Catalyzes the methylthiolation of N6-threonylcarbamoyladenosine (t(6)A), leading to the formation of 2-methylthio-N6-threonylcarbamoyladenosine (ms(2)t(6)A) at position 37 in tRNAs that read codons beginning with adenine.
Synonyms: FLJ20342
Tractability: Antibody: UniProt predicts a signal peptide or a membrane-spanning region. PROTAC: ubiquitination databases record sites on it; its protein half-life has been measured.
Target class: Enzyme; Transferase
Gene: Protein-coding gene on chromosome 6 (20,534,447 to 21,232,855, forward strand). Ensembl gene ENSG00000145996.
Subcellular location: Endoplasmic reticulum membrane
Pathways (Reactome):
Metabolism of RNA: tRNA modification in the nucleus and cytosol
Gene Ontology:
Molecular function: protein binding; tRNA (N(6)-L-threonylcarbamoyladenosine(37)-C(2))-methylthiotransferase activity; 4 iron, 4 sulfur cluster binding; catalytic activity; iron-sulfur cluster binding; methylthiotransferase activity; transferase activity
Biological process: maintenance of translational fidelity; tRNA methylthiolation; tRNA modification
Cellular component: endoplasmic reticulum membrane; membrane; endoplasmic reticulum; rough endoplasmic reticulum
Genetic constraint (gnomAD): Loss-of-function variants: 11 observed, 28.3 expected, observed/expected ratio (o/e) 0.39, 90% interval 0.24 to 0.64. The upper end of that interval is the gene's LOEUF score, 0.64, which puts it in group 2 of 6, group 1 being the genes least tolerant of losing a copy. Missense variants: 373 observed, 425.44 expected, observed/expected ratio (o/e) 0.88, 90% interval 0.81 to 0.95. Synonymous variants: 154 observed, 157.94 expected, observed/expected ratio (o/e) 0.98, 90% interval 0.85 to 1.12.
Homologues: Orthologues: chimpanzee CDKAL1 (99% identical), macaque CDKAL1 (98% identical), pig CDKAL1 (94% identical), rabbit CDKAL1 (91% identical), dog CDKAL1 (91% identical), mouse Cdkal1 (91% identical), guinea pig CDKAL1 (86% identical), tropical clawed frog cdkal1 (77% identical), rat LOC120093069 (76% identical), Drosophila melanogaster CG6550 (56% identical), Caenorhabditis elegans Y92H12BL.1 (37% identical), zebrafish cdkal1 (27% identical). Paralogues in human: CDK5RAP1 (22% identical).
Diseases named in the same sentence as CDKAL1 in open-access papers:
CDKAL1 is named in the same sentence as 69 diseases in open-access papers, as found by Europe PMC text mining. Sharing a sentence is not in itself a finding about the gene and the disease. The quoted sentences say what the papers report.
type 2 diabetes (90 papers, 2007 to 2026). "These suggest that CDKAL1 gene expression affects an individual’s susceptibility to Type 2 diabetes mellitus." (PMID 39561140, 2024). "In multiple human populations, CDKAL1 variants are associated with risk for type 2 diabetes mellitus and decreased insulin secretion." (PMID 38092373, 2024). "Previous studies have shown that the rs10946398 polymorphism of the CDKAL1 gene affects insulin secretion by pancreatic β-cells and is a risk factor for type 2 diabetes and gestational diabetes." (PMID 37628646, 2023). "Certain polymorphisms in the CDKAL1 gene have been shown to be associated with a decrease in insulin sensitivity of the body’s tissues and an increased risk of type 2 diabetes." (PMID 37628646, 2023). "Many studies to date have confirmed the association between CDKAL1 gene polymorphisms and the occurrence of type 2 diabetes and gestational diabetes." (PMID 37628646, 2023). "Initially, variants at type 2 diabetes risk loci affecting insulin secretion were tested for their association with birthweight and it was found that fetal risk alleles at the CDKAL1 and HHEX-IDE loci were associated with a lower birthweight." (PMID 33569631, 2021). "We aim to explore the association between CDKAL1 rs10946398 gene polymorphism and susceptibility to type 2 diabetes in different populations." (PMID 34977253, 2021). "Genetic variants of CDKAL1, which maps to chromosome 6p22.3, are strongly linked to an increased risk of developing type 2 diabetes and obesity." (PMID 33500527, 2021). "Type 2 diabetes (T2D) is the most frequent type of diabetes, and genetic variations in the CDKAL1 gene are associated with T2D." (PMID 34769366, 2021). "The existing studies on the association between CDKAL1 rs10946398 gene polymorphism and susceptibility to type 2 diabetes are inconsistent across populations." (PMID 34977253, 2021). "It is worth noting that the marker showing the strongest phenotypic effect (rs6908425) is mapped to CDKAL1, which is also associated with type 2 diabetes mellitus (T2DM)." (PMID 34899832, 2021). "GWAS revealed relationships between several SNPs in CDKAL1, encoding cyclin-dependent kinase 5 regulatory subunit associated protein 1-like 1 (CDKAL1), and type 2 diabetes risk." (PMID 33594477, 2021). "CDKAL1 represents one of the strongest signals of association with type 2 diabetes across diverse ancestries, with minimal heterogeneity in allelic effects between populations." (PMID 32944759, 2021). "Previous research suggests that CDKAL1 rs7756992 is associated with type 2 diabetes in several populations." (PMID 32764395, 2020). "A study including Finnish men demonstrated that CDKAL1 (rs7754840) was associated with increased risk for type 2 diabetes, likely via impairing insulin secretion." (PMID 32228543, 2020). "Previous studies in European and Asian populations found that CDKAL1 is associated with type 2 diabetes, and the C allele of rs7754840 was associated with the highest risk for diabetes." (PMID 32228543, 2020). "KCNQ1 rs2237892 and CDKAL1 rs10946398 were identified as a susceptibility gene for type 2 diabetes in GWAS, and each of these genes is associated with β-cell dysfunction." (PMID 31623129, 2019). "In this Taiwan-based study, we have attempted to validate the association between CDKAL1 rs10946398 and type 2 diabetes." (PMID 30185902, 2018). "In this study, we found a significant association between CDKAL1 rs10946398 and type 2 diabetes among Taiwanese individuals." (PMID 30185902, 2018). "The cytosolic ms2A modification is required for the production of proinsulin, which explains why single-nucleotide polymorphisms (SNPs) in the Cdkal1 gene (a MiaB homolog) are a risk factor for type II diabetes." (PMID 30450093, 2018). "Evidence from candidate gene studies, and the first GWAS of birth weight suggested that the type 2 diabetes risk alleles at the CDKAL1, ADCY5, and HHEX-IDE loci were also associated with lower birth weight." (PMID 28293907, 2017).
type 2 diabetes (continued). "Variants within CDKAL1 are strongly linked to an increased risk of developing type 2 diabetes and obesity." (PMID 29031721, 2017). "Numerous genetic studies have found that several SNPs within the CDKAL1 region are associated with type 2 diabetes among multiple ethnic populations." (PMID 28821857, 2017). "In summary, we identified CDKAL1 rs7756992 as a susceptibility locus for DR in a Chinese population with type 2 diabetes." (PMID 28821857, 2017). "CDK5 Regulatory Subunit-Associated Protein 1-like 1 (CDKAL1) was identified as a susceptibility gene for type 2 diabetes and body mass index in genome-wide association studies." (PMID 28779110, 2017). "The regulation of Cdkal1 with obesity and the strong association between obesity and type 2 diabetes suggested further investigation into adipose Cdkal1 was warranted." (PMID 29031721, 2017). "Polymorphic variants within the CDKAL1 locus are strongly associated with increased risk of developing type 2 diabetes by GWAS and dozens of replication studies in diverse populations." (PMID 29031721, 2017). "We investigated the association between common type 2 susceptibility variants of CDK5 regulatory subunit associated protein 1-like 1(CDKAL1) and therapeutic responses to anti-diabetic agents among patients with type 2 diabetes." (PMID 27139004, 2016). "Of the 66 known type 2 diabetes variants we only found evidence of deviation from additivity for the SNP rs7756992 at the CDKAL1 locus (MAF = 0.27; pDOMDEV = 5 × 10−4)." (PMID 26961502, 2016). "Contrary to previous findings, we provide evidence against a role for dysregulated expression of CDKAL1-v1 in mediating the association between intronic SNPs in CDKAL1 and susceptibility to type 2 diabetes." (PMID 25634229, 2015). "It has been reported that the type 2 diabetes-associated risk alleles at this locus are associated with lower levels of a non-coding CDKAL1 splice variant, CDKAL1-v1, which regulates CDKAL1 activity." (PMID 25634229, 2015). "The lead type 2 diabetes-associated SNP, rs7756992, was still associated with CDKAL1-v1 levels when taking into account rs9366357, although the effect size was reduced and far smaller than the effect of rs9366357 (β = −0.34, p = 0.01)." (PMID 25634229, 2015). "In a simple linear regression model, expression of CDKAL1-v1 was associated with the lead type 2 diabetes-associated SNP, rs7756992, in whole blood and islets." (PMID 25634229, 2015). "Intronic single nucleotide polymorphisms (SNPs) in the CDKAL1 gene are associated with risk of developing type 2 diabetes." (PMID 25634229, 2015). "This study reports association of CDKAL1-related SNPs with insulin resistance, a clinical marker related to type 2 diabetes in a cross-sectional cohort of Greek children and adolescents of European descent." (PMID 24695378, 2014). "Because two intronic CDKAL1 variants (rs7754840 and rs7756992) that are positioned close to rs9368197 have been associated with type 2 diabetes and GDM in GWA studies, we also analyzed the genetic patterns surrounding these two variants." (PMID 25222615, 2014). "Variations in CDKAL1 have been reported to be associated with impaired insulin secretion and the increased risk of type 2 diabetes." (PMID 23990951, 2013). "The association study of SNPs and type 2 diabetes related quantitative traits showed that subjects carrying the CDKAL1 risk allele had higher plasma glucose 30 min in OGTT (β = 0.01669 per G allele for lnFPG; p = 0.0006)." (PMID 23990951, 2013). "The association of CDKAL1 (rs7756992) with type 2 diabetes has been well established in Han Chinese." (PMID 23990951, 2013). "Together, despite a lack of direct biological evidence reported to date, these association data support the possible contribution of causal variants at CDKAL1 to the pathogenesis of type 2 diabetes." (PMID 23173044, 2012).
type 2 diabetes (continued). "Type 2 diabetes risk conferred by CDKAL1 variant(s) can be appreciably modified by BMI as a consequence of a gene–environment (or diet) interaction, in relation to ethnic-group-specific dietary habits, e.g., a Western diet vs. an East Asian diet." (PMID 23173044, 2012). "In this context, data presented from two Japanese populations support the opposing effects of CDKAL1 variants on BMI and type 2 diabetes." (PMID 23173044, 2012). "The CDKAL1 gene is among the best-replicated susceptibility loci for type 2 diabetes, originally identified by genome-wide association studies in humans." (PMID 23173044, 2012). "Based on the findings in mice, we tested genetic association of CDKAL1 variants with BMI, as a measure of adiposity, and type 2 diabetes in Japanese." (PMID 23173044, 2012). "Molecular variants that linked the human CDKAL1 gene to increased type 2 diabetes susceptibility are located in the middle of a large intron of CDKAL1." (PMID 23173044, 2012). "A cluster of single nucleotide polymorphisms (SNPs) in intron 5 of the CDKAL1 gene were associated with type 2 diabetes in populations of European and Asian descent." (PMID 23173044, 2012). "This supports the bidirectional genetic effects of Cdkal1–reduced adiposity and increased susceptibility to type 2 diabetes." (PMID 23173044, 2012). "To evaluate this possibility, we plotted effect sizes for type 2 diabetes against BMI in the control group (as the population mean data) for the individual case-control studies that investigated disease association at CDKAL1." (PMID 23173044, 2012). "Individual genes associated with Ps, such as Cyclin-dependent kinase 5 regulatory subunit associated protein 1-like 1 (CDKAL1), are also associated with type 2 diabetes." (PMID 21299865, 2011). "Recent genome-wide association studies have identified CDKAL1 (cyclin-dependent kinase 5 regulatory subunit associated protein 1-like 1) as a susceptibility gene for type 2 diabetes, which has been replicated in several populations." (PMID 21151568, 2010). "Genome-wide association studies have shown that several single-nucleotide polymorphisms (SNPs) in intron 5 of the CDKAL1 gene are associated with type 2 diabetes." (PMID 21151568, 2010). "In this study, we found that pancreatic β cells from mice null for CDKAL1, which was identified as a susceptibility gene for type 2 diabetes in humans, have a reduced first-phase insulin release in vitro." (PMID 21151568, 2010). "Our results support previous findings that these variants in CDKN2A/B and CDKAL1 individually contribute to the risk of type 2 diabetes in the Han Chinese population, but imply some ethnic differences between Europeans and Asians." (PMID 20161779, 2010). "Genome-wide association studies have identified CDKAL1 variants as risk factors for type 2 diabetes mellitus (DM) and chronic kidney disease (CKD), but whether CKD arises independently of diabetes has remained elusive." (PMID 41904323, 2026). "On the contrary rs7766070 of the CDKAL1 gene has an OR greater than 1 which may indicate a risk effect on the population for type 2 diabetes mellitus." (PMID 39561140, 2024). "Genetic variations in the CDKAL1 gene are linked to type 2 diabetes in different ethnic groups." (PMID 36923941, 2023). "In addition, the mutation of CDKAL1 gene causes type 2 diabetes, for reasons that CDKAL1 dysfunction results in aberration of the ms2t6A modification of cytoplasmic tRNALys, which leads to misreading of lysine codons in proinsulin." (PMID 36362385, 2022). "Polymorphisms in the CDKAL1 gene are reported to be associated with type 2 diabetes mellitus in several human populations, and the CDKAL1 gene is involved in the metabolism of insulin that affects glucose mediated mechanisms, crucial for feed-efficiency and other growth and adaptation traits." (PMID 36353101, 2022). "Thus, people with CDKAL1 type 2 diabetes risk variants showed a better glycaemic response to DPP-4i." (PMID 33594477, 2021).
type 2 diabetes (continued). "We have previously shown that type 2 diabetes risk variants in CDKAL1 and HHEX were associated with decreased beta-cell glucose sensitivity in nondiabetic individuals; however, these associations have not been tested in a larger cohort that includes subjects with abnormal glucose tolerance." (PMID 32944759, 2021). "Of the 30288 subjects, including 19272 controls and 11016 T2DM patients, we found that CDKAL1 RS10946398 gene polymorphism locus is associated with type 2 diabetes mellitus in different ethnic groups, and the degree of correlation is different in different genetic models." (PMID 34977253, 2021). "Our results from the blood glucose analysis validated well-established gene loci associated with type 2 diabetes with common SNPs in CDKAL1, SLC30A8, SND1-PAX4, IDE-KIF11-HHEX, CDKN2A-CDKN2B, KCNQ1 and CDC123,33,37,38 and identified a novel locus associated with FBG in DENND5B." (PMID 32355288, 2020). "We did not observe significant interactions by five single nucleotide polymorphisms (SNPs) related to type 2 diabetes (CDKAL1 rs7756992, CDKN2A/B rs10811661, KCNJ11 rs5215, KCNQ1 rs163184, and PEPD rs3786897) in the association between coffee and the risk of type 2 diabetes." (PMID 32722593, 2020). "In addition, evidence from studies of other type 2 diabetes loci is accumulating for association between the fetal risk alleles at CDKAL1 and HHEX-IDE and lower birth weight." (PMID 32082357, 2019). "The CDKAL1 locus, implicated in type 2 diabetes, is a perfect example of these issues." (PMID 29031721, 2017). "Further understanding of whether genetic variation linked to type 2 diabetes within the CDKAL1 locus leads to decreased CDKAL1 expression and altered mitochondrial function in human patients will be an important next step in our investigations." (PMID 29031721, 2017). "There were exceptions for the FTO–BMI association and the CDKAL1–type 2 diabetes association." (PMID 26961502, 2016). "Additionally, several genome-wide association analyses identified that CDKAL1 multiple single nucleotide polymorphism loci were associated with human susceptibility of type 2 diabetes." (PMID 26504476, 2015). "We next sought to determine whether CDKAL1-v1 is similarly regulated in human pancreatic islets—the primary tissue of interest with respect to the type 2 diabetes association." (PMID 25634229, 2015). "Interestingly, this non-coding RNA has the same targeting miRNA as full length CDKAL1, of which is a type 2 diabetes risk factor associated with insulin secretion." (PMID 25477902, 2014). "CDKAL1-related variants have previously been associated with type 2 diabetes and insulin response." (PMID 24695378, 2014). "In addition, simulation analysis indicated that a type 2 diabetes risk variant in CDKAL1 (rs7754840) was selected in East Asians ∼6,900 years ago." (PMID 25222615, 2014). "In accordance with the findings in mice, a nominally significant (P<0.05) association between CDKAL1 rs4712523 and BMI was replicated in 2 Japanese general populations comprising 5,695 and 12,569 samples; the risk allele for type 2 diabetes was also associated with decreased BMI." (PMID 23173044, 2012). "Interestingly, since 2007, numerous studies have associated CDKAL1 SNPs with a cardiovascular disease (CVD) risk factor: Type 2 Diabetes (T2D)." (PMID 22216278, 2011). "Interestingly, our GWAS also showed CDKAL1, a gene previously shown to be associated with type 2 diabetes (T2D), to be marginally associated with IS in our data." (PMID 22384361, 2011). "A variant of the CDKAL1 gene was reported to be associated with type 2 diabetes and reduced insulin release in humans; however, the role of CDKAL1 in β cells is largely unknown." (PMID 21151568, 2010). "The function of CDKAL1 is poorly understood but the gene has been associated with type-2-diabetes, and could also possibly be a psoriasis risk locus." (PMID 21152001, 2010).